CD4 (CD4 molecule)
Diseases named in the same sentence as CD4 in open-access papers (continued):
Sharing a sentence is not in itself a finding about the gene and the disease.
tumor (continued). "In concordance with more aggressive tumor growth in KI mice, immunophenotyping of tumor-infiltrating lymphocytes (TILs) indicates that abundance of total CD3+ immune cells, CD4+ T cells, CD8+ T cells and CD11c+ dendritic cells was substantially lower in tumors from KI hosts vs WT control." (PMID 33462142, 2021). "CD4+ T helper cells induce and intensify more permanent tumor immune control, epitope spreading, CD8+ T cell expansion and survival, as well as tumor immune cell infiltration." (PMID 33583769, 2021). "In general, CD4+ Th1, infiltrating CD8+ CTLs and CD103+ cDC1s contribute to the main anti-tumor effects observed upon the induction of various immunomodulatory treatment regimens, including checkpoint inhibitors, oncolytic viruses, radiotherapy, chemotherapy, or adoptive T-cell therapy." (PMID 34885215, 2021). "In cancer, the main anti-tumor immune responses are mediated by the tumor antigen recognizing CD8+ T cells after their activation and differentiation into effector cytotoxic T lymphocytes (CTLs) by APCs and CD4+ T cells." (PMID 34944867, 2021). "Since there was no significant component of the CD4 progenitor cells in the tumor samples, they were excluded from this study." (PMID 33955820, 2021). "Both OB-RES and DIO therapy-treated mice displayed a significant increase in CD44+CD4+ TILs at day 27–28 compared to no therapy controls, likely due to tumor-induced reductions in the CD44+CD4+ TIL population that occurred in the absence of therapy." (PMID 34064933, 2021). "The main mechanisms used by Tregs to eliminate protective antitumor immunity contributing on tumor progression, include direct inhibition of effector T-cells, dysfunction of DCs via IL-10 and TGF-β and interruption of CD4 T-cell-mediated generation of CD8 T-cell cytotoxic responses." (PMID 34640606, 2021). "Pre- and post-therapy paired biopsies of tumor tissues, including LNs and bone marrow (BM), were performed in six patients, all of which exhibited a significant number of infiltrated CD3+ (CD8+ > CD4+) T cells and macrophages following the combination treatment." (PMID 35008305, 2021). "CD4+ T cells play multiple roles in controlling tumor growth and increasing IFN-γ+ T-helper 1 cell population could promote cell-mediated anti-tumor immune response." (PMID 33791306, 2021). "Furthermore, immunohistochemistry analysis revealed that there were more T cells, including CD4+ T cells, CD8+ T cells, and macrophages, in the tumor nodules of liver tissue in the treated mice than in the control mice." (PMID 33710817, 2021). "S100A8 expression in tumor cells (TCs) and immune cells (ICs) was assessed by immunohistochemistry, and its association with clinicopathologic features and infiltration of other IC subsets including CD4+, CD8+, and FOXP3+ tumor-infiltrating lymphocytes (TILs) and PD-L1+ ICs was evaluated." (PMID 33146829, 2021). "Although it was thought that TILs present in the tumor or TME were due to inflammation, it has been proved by several studies that TILs consist of a larger portion of tumor-specific T cells, including CD8+ CTLs and CD4+ T helper (Th) cells." (PMID 34553029, 2021). "The CD4+ but not CD8+ T cells were essential for the generation of the anti-tumor response, depleting CD4+ T cells abrogated this response and a corresponding increase in CD4+ tumor-infiltrating lymphocytes (TILs) was associated with tumor regression." (PMID 33859638, 2021). "CODEX analysis revealed global prognostic spatial patterns that were predictive of clinical response, including a localized enrichment of tumor and CD4+ T cells (CN-8) in responders and of Tregs (CN-10) in nonresponders." (PMID 34795254, 2021). "Immune inflamed tumors, such as melanoma, are characterized by the infiltration of CD4+ and CD8+ T cells within the tumor parenchyma, suggesting the presence of a pre-existing anti-tumor response that has been dampened by an immunosuppressive microenvironment or by intrinsic T-cell tolerance." (PMID 34502458, 2021).
tumor (continued). "Others, however, have shown tasquinimod to block the trafficking of myeloid derived suppressive cells (which inhibit the anti-tumor activity of CD8 and CD4 cells), change the polarization of tumor-associated macrophages into M1 phenotype, and improve efficacy of PD-L1 blockade." (PMID 34975408, 2021). "Depletion of CD8+ T cells did not result in any appreciable change in anti-tumor effect, whereas depletion of either CD4+ T cells or NK cells resulted in abrogation of the therapeutic effect in virus-injected tumors." (PMID 33665363, 2021). "CD4+T cells can secrete IFN-γ, IL-2, and TNFα cytokines to interfere with tumor development." (PMID 34804019, 2021). "Immunosuppressive MDSCs have been isolated in TDLN and shown to dampen anti-tumour T cell responses, reducing T cell activation and CD4+/CD8+ T cell numbers but not T cell effector function." (PMID 34141724, 2021). "Treatment with anti-CD4 did not affect tumor inhibition and tumor volumes were similar to vaccine alone (p>0.49 for all)." (PMID 34526999, 2021). "In both tumor models, GPR171 blockade proportionally increased intratumoral CD3+ T cells and CD8 + T cells in CD45+ immune cells and increased the ratio of CD8+ to CD4+ T cells within tumors." (PMID 34615877, 2021). "During priming, CD4+ and CD8+ T cells can be polarized to distinct subpopulations of effector cells, such as EM CD8+ T cells, also commonly known as cytotoxic T lymphocytes capable of counteracting or terminating tumor progression." (PMID 34070750, 2021). "We analyzed the density, quality, and temporal distribution of tumor-infiltrating immune cells (CD3+, CD4+, CD8+, Foxp3+, and CD57+), as well as molecular and immunophenotypic biomarkers of tumor immunogenicity, along the development of colorectal precursor and invasive lesions." (PMID 34575971, 2021). "Furthermore, mice transfused with CD4+ T cells plus TCN and IL‐17A neutralizing antibody, showed decreased the proliferation of GC tumor cells as well as IL‐17A production, compared to mice transfused with CD4+ T cells plus TCN and control IgG." (PMID 34185422, 2021). "Our study describes a combinatorial approach to overcome the lack of a pre-existing immune response and ultimately convert a cold tumor into a hot tumor by increasing CD8+ and CD4+ T cell infiltration and by enhancing T cell responses by neutralization of suppressive signals in the TME." (PMID 34771674, 2021). "Indeed, chimeric antigen receptor (CAR) transduced CD4+ (CAR4) and CD8+ (CAR8) T cell subsets each respond to antigen, with individually defined roles in the anti-tumor response." (PMID 33669271, 2021). "ITLPD-GI tumor cells typically exhibit a CD2+, CD3+, CD5+, and CD4+ or CD8+ phenotype." (PMID 34830926, 2021). "Human tumor-infiltrating lymphocytes (TILs) such as CD8+ cytotoxic T cells, conventional CD4+ T cells, T follicular helper cells (TFH), B cells, and natural killer cells are generally associated with favorable (anti-tumor) immune responses, together with γδ T cells and eosinophils." (PMID 34621785, 2021). "We next compared the differences in the IFN-γ+CD4+ and IL-21+CD4+ T cell frequencies between tumor and adjacent non-tumor tissues." (PMID 34026621, 2021). "The number of tumors infiltrating lymphocytes, including CD3+T cells, CD20+B cells, and especially CD4+ and T-bet+Th1 cells, was increased in tumor tissues in the absence of more mature DCs." (PMID 34553849, 2021). "In the present study, compared to auto-CD4+ T cells, intratumorally injected AAA-CD4+ T cells significantly expanded in the tumor and produced high levels of IFN-γ as early as 4 h post-therapy, which may induce initial immunogenic cancer cell death." (PMID 34625113, 2021). "Finally, we found that approximately half of the IL-21+CD4+ T cells in the tumor tissues were IFN-γ positive (45.6 ± 5.2%) and that IL-21+CD4+ T cells were rarely IL-4 (0.8 ± 0.3%) or IL-17 (1.6 ± 0.5%) positive." (PMID 34026621, 2021).
tumor (continued). "The subsequent assays revealed a negative correlation between IGF2BP2 and multiple tumor-infiltrating immune cells, such as B cells, CD4+ T cells, follicular helper T cells, and Tregs." (PMID 33816266, 2021). "DCs capture tumor antigens and present them within major histocompatibility class (MHC) molecules to the naïve CD4+ and CD8+ T lymphocytes, resulting in their activation, proliferation and differentiation in effector CD4+ T helper (Th)cells and CD8+ cytotoxic T lymphocytes (CTLs)." (PMID 34830312, 2021). "Moreover, local tumor immune-related cells (CD3+, CD4+, CD8+, PD-1+, and Foxp3+ T cells) were also evaluated." (PMID 34758773, 2021). "Similarly, CAFs derived from other tumor types also promote the expression and recruitment of FOXP3+CD4+ T cells into the tumor milieu." (PMID 34203869, 2021). "CD4+ T cells genetically unresponsive to activin-A, failed to elicit effective anti-tumor properties and displayed an exhausted molecular signature governed by the transcription factors Tox and Tox2." (PMID 34548096, 2021). "Furthermore, ABCG1 deficiency in macrophages resulted in changed intrinsic cytokine production, augmented NK cells and CD4+ T cell infiltration in the TME, and prevented tumor growth." (PMID 34742349, 2021). "Interestingly, with MF progression, the LGALS9-CD47 interaction switches places: in plaque MF, exhausted BTLA+ CD4+ T cells express CD47, and the tumor cells express ligand LGALS9, but in tumor MF, the opposite occurs." (PMID 34885092, 2021). "In addition, rSmeg-hMIF-hIL-7 treatment led to enhanced activation of CD4+ and CD8+ T cells in the tumor regions of vaccinated mice, also contributing to the anticancer effect." (PMID 34389619, 2021). "On the contrary, Tox and Tox2 did not bind on the genetic locus of Jun in tumor-infiltrating CD4+ T cells from CD4/ALK4-KO mice." (PMID 34548096, 2021). "Furthermore, tumor-specific, IFN-γ-producing CD8+ and CD4+ T cell responses were detected in the memory T-cell subset, defined by CD44high obtained from the mouse spleen." (PMID 35008305, 2021). "Among other theories, the observation that gut microbiota is involved in the functions of intestinal CD4+ and CD8+ T, with anti-tumor immunological activity, is gaining strength and this could impact the efficacy of ICIs." (PMID 33670634, 2021). "It was determined that DFMO-treated tumors exhibited an increase in F4/80 (macrophage marker), CD86 (a T cell-costimulatory marker) and infiltration of T lymphocytes into the tumor environment as demonstrated by increased CD3, CD4 and CD8 expression in DFMO-treated tumor groups." (PMID 34947972, 2021). "Others have suggested that CD4+ T cells can reject MHC Class II negative tumor cells through interplay with other infiltrating macrophages and NK cells." (PMID 33968044, 2021). "The cancer vaccine is a kind of vaccine that mobilizes the immune system to produce cytotoxic T-lymphocytes with anti-tumor effect and long-term memory CD8+ T cells, while the functional activity of producing a CD8+ /CD4+ T cell response is restricted by human leukocyte antigen (HLA)." (PMID 34150736, 2021). "On the other hand, tumour infiltrating lymphocytes (TILs) are also found in MPM, but CD4+ and CD8+ TILs might have decreased cytotoxic effects through T-regulators and high expression of immune checkpoints." (PMID 34206956, 2021). "CHK1i+LDHU triggered a strong anti-tumour T cell response demonstrated by the very high proportion of tumour antigen reactive CD4+ and CD8+ T cells in the blood (and spleen; data not shown) of treated mice." (PMID 34359633, 2021). "In contrast, the regimen used in this study (weekly treatment of anti-CD4) did not elicit any autoimmune symptoms, while the anti-tumor response was retained." (PMID 34493727, 2021). "At the end of the study, PRGN-2009–treated mice depleted of CD4+ T cells displayed larger tumor volumes than nondepleted PRGN-2009–treated mice." (PMID 33651712, 2021).
tumor (continued). "Additionally, FERMT2 expression showed a similar relationship with tumor purity and the infiltration of CD8+ T cell, CD4+ T cell, Macrophage, Neutrophil, and Dendritic cell in LUAD and LUSC." (PMID 33934696, 2021). "In contrast, in tumor-bearing mice, PD-1 expression was higher in AMPK-deficient CD4+ T cells, but not in CD8+ T cells." (PMID 34649584, 2021). "Since in vivo testing revealed a remarkable increase in total CD8+ T-cell infiltrates in tumors of Ogr1−/− mice, we further constructed mouse models of conditional knockout of Ogr1 in CD4+ and CD8+ T cells, which markedly resulted in the lightening of the tumor load." (PMID 34158625, 2021). "On the basis of these findings, we assessed whether adoptive transfer of lung tumor-infiltrating CD4+ T cells treated ex vivo with activin-A could reduce lung tumor burden and enhance the overall survival of LLC-OVA tumor-bearing mice." (PMID 34548096, 2021). "Since CD4+ T cells, CD8+ T cells, and NK cells are crucial antitumor components and potential targets of IFNα, we tested if these cells were required for the IFNα-mediated tumor suppression of CRPC." (PMID 34771735, 2021). "Our results demonstrate for the first time the impact of tumor-derived extracellular vesicles and non-cell-mediated tumor-suppressive effects on CD4+ CAR T cell efficacy in a preclinical setting." (PMID 32296437, 2020). "CD4+ and CD8+ T cells that were specific for a wide range of NY-ESO-1 epitopes were also observed in the peripheral, highlighting the potential use of NY-ESO-1 IMX vaccine in various NY-ESO-1 positive tumours." (PMID 33207697, 2020). "The CD4+:CD8+ T cell ratio is often used as a simple measure to determine the overall balance of T cell function in cancer, providing prognostic information when measured in the tumor and tumor-immune interface." (PMID 32763154, 2020). "M1 macrophages are able to: (i) release pro-inflammatory cytokines such as IL-12, IFN gamma, IL-1, IL-23, and iNOS; (ii) reeducate the DC and CD4 + T cells; and (iii) activate CD8 + T cells and, as a result, promote an immune response against the tumor and prevent tumor progression." (PMID 33117331, 2020). "This study identified an important role for CD4+ T cell-specific antigens in the tumor microenvironment, even in tumors that did not express MHC class II." (PMID 33298945, 2020). "Notably, lymphocytes play a critical part in cellular immunity, including CD4+ and CD8+ cells, especially tumor-infiltrating T lymphocytes, which suppress the proliferation and migration of tumors through apoptosis." (PMID 32711514, 2020). "Tumor cells can express either CD4 or CD8, with the majority expressing CD4." (PMID 32448357, 2020). "The E2F2 expression in LGG showed a positive correlation with infiltrating levels of B cells, CD4+ T cells, macrophages, neutrophils, and dendritic cells but not with tumor purity." (PMID 33381564, 2020). "Alternatively, numerous subsets of CD25+, CD4+ and CD8+ lymphocytes may coexist in the tumor microenvironment, which could differ in phenotypes, functions and locations in different time perspectives." (PMID 32484812, 2020). "CC chemokines (or β-chemokines) are 28 chemotactic cytokines with an N-terminal CC domain that play an important role in immune system cells, such as CD4+ and CD8+ lymphocytes, dendritic cells, eosinophils, macrophages, monocytes, and NK cells, as well in neoplasia." (PMID 33076281, 2020). "Accordingly, tumor burden resulted in inverse correlated with the frequencies of circulating lymphocytes (p = 0.03), including CD3+ and CD4+ T cells (p = 0.04 and p = 0.02, respectively), as well as pDC and mDC frequencies (p = 0.006 and p = 0.001, respectively)." (PMID 32731406, 2020). "Since the in vitro culture of CD4+ CD25high regulatory T cells under hypoxia also induced the expression of IL-17, the authors suggested that CRC-derived CD68+ cells attracted Foxp3+ Tregs at the tumor site where hypoxia induced their expression of IL-17." (PMID 32121394, 2020).
tumor (continued). "Furthermore, we discovered the GC microenvironment with increased CD4+FOXP3+ T cells and CD8+ T cells (the High‐High group) had a robust IFN‐γ response and PDL1 expression, suggesting a strong immune activation in the tumor." (PMID 32377339, 2020). "Furthermore, administration of EGCG was able to partly restore the percentages of CD4+ T helper cells and CD8+ cytotoxic T cells in the spleen and tumor tissues, indicating the anti-tumor immune response in tumor-bearing mice is enhanced by EGCG treatments." (PMID 32290071, 2020). "Finally, Robert Schreiber from Washington University discussed approaches in characterizing CD8+ and CD4+ T cell epitopes and TCR repertoire in murine tumor models." (PMID 32245497, 2020). "Previous studies confirmed that CD4+ T-cells can differentiate into distinct subsets with opposite functions, including blocking CD8+ T-cell activation and NK cell killing, recognizing cancer antigens, and aiding CD8+ T-cells in tumor immune responses." (PMID 32028264, 2020). "Combined with the release of cytokines from tumour cells, this promotes the activation of CD4+ and CD8+ T cells, which traffic to sites of established tumour cell growth and mediate anti-tumour immunity, releasing more inflammatory cytokines into the tumour microenvironment." (PMID 31947615, 2020). "Thus, an increase in the CD4 + and CD8 + populations is observed when the size of the tumor increases." (PMID 33026171, 2020). "This notion is supported by the increased frequencies of CD4+ effector cells (Th1, Th2, and Th17) and CD8+ effector cells in TDLNs, the unique kinetics of plasma IFNγ levels, and the impaired accumulation of T cells, B cells and NK cells in the lung and tumor." (PMID 32770025, 2020). "Another study showed that the use of ex vivo adenovirus vector in increasing CX3CL1 expression in dendritic cells and introducing these cells into a tumor increased the anti-tumor response, in particular the homing of CD8+ T cells and CD4+ T cells to the tumor." (PMID 32466280, 2020). "IL-12, IFN-γ, CD4+ and CD8+ T cells are responsible for retaining the occult tumor cells." (PMID 33323544, 2020). "Total T cells, CD4+ cells, CD8+ cells, the CD4+/CD8+ cell ratio, DCs and monocytes in tumor tissue may have significant roles in predicting the homeostasis of the host antitumor immune response." (PMID 32131750, 2020). "The MHC class-II neoantigens may shape the tumor immunity and response to immunotherapy, indicating the ignored MHC-II neoantigens and CD4+ T cells as key factors that influence the response to immunotherapy." (PMID 33585439, 2020). "Enhanced numbers of GzmB producing CD4+ and CD8+ T cells in tumor patients after combination treatment with antibodies against PD-1 and CTLA-4 have previously been described, but this study did not perform a detailed characterization of the GzmB producing cells." (PMID 32226027, 2020). "In line with this, CEA-TCB treatment also increased the frequency of intra-tumor CXCR3+ CD8+ and CD4+ T-cells, corroborating the relevance of the CXCL10-CXCR3 axis in mediating the attraction of T-cells leading to increase of intra-tumor T-cell infiltration upon TCB treatment (and unpublished data)." (PMID 33330050, 2020). "Therapy-induced tumor rejection was dependent on CD4+ and CD8+ T cells, but not on NK or B cells, and relied on intact IFN and mitochondrial antiviral signaling protein (MAVS) signaling in the host." (PMID 31740809, 2020). "Tumor-infiltrating lymphocytes (TIL) are primarily composed of CD8+ CTLs, conventional CD4+ T helper cells and regulatory T cells (Tregs), which in most studies are defined by CD4+ CD25+ FoxP3+ expression." (PMID 32117316, 2020). "There were no significant changes in tumor monocytic MDSCs (M-MDSCs), eosinophils, dendritic cells (DCs), CD4+ T cells, or CD8+ T cells." (PMID 32780726, 2020).